CD4 (CD4 molecule)
Diseases named in the same sentence as CD4 in open-access papers (continued):
Sharing a sentence is not in itself a finding about the gene and the disease.
viral infection (continued). "In addition to the crucial role of EZH2 in TFH/TH1 cell differentiation, the present study also found that EZH2 is a prerequisite for the efficient expansion of CD4 T cells (including both TFH and TH1 cells) during acute viral infection." (PMID 32999031, 2020). "However, IL-21 also displays anti-viral effects, as mice models have shown that CD4+ T cell produced IL-21 is critical for the differentiation, function and survival of anti-viral CD8+ T cells able to contain chronic virus infections." (PMID 33228556, 2020). "However, during many acute viral infections, the period for peak CD8 or CD4 T cell responses and the window for PB detection in peripheral blood are relatively short." (PMID 32669297, 2020). "Egr2 negative PD-1high MP CD4 T cells are impaired in homeostatic proliferation and adaptive responses against viral infection but display inflammatory responses to innate stimulation such as IL-12." (PMID 32709717, 2020). "The restoration of strong CD4 T cell immunity against HIV is needed to support the continuing evolution of T and B cell responses needed to reconstitute normal immune control of this viral disease." (PMID 32462053, 2020). "Further, proficient CD4+ T-cell response and moderate CD8+ T-cell response also demarcate the specific engagement of Th2 and Th1 type immune responses that play a vital role against viral infections." (PMID 32143695, 2020). "To date, CD4+ and CD8+ T cells capable of co-producing IFN-γ, TNF-α and IL-2 (namely multifunctional CD4+ and CD8+ T cells) have been considered to be important for controlling various viral infections." (PMID 33142799, 2020). "CD4+ T cells could elicit protective antibody responses and generate both B-cell and CD8+ T-cell memory responses during the viral infection." (PMID 32104691, 2020). "On the one hand, activated CD4+ T cells are the main targets for viral replication; thus, the virus may enhance CD3-TCR signaling to render infected T cells fully permissive for viral infection and spread." (PMID 32075764, 2020). "Decrease the doses of immunossuppressive drugs is based on the experience with other viral infections that may affect KTRs, and lower counts of CD3+, CD4+, CD8+ cells exhibited by these patients." (PMID 32550702, 2020). "CD4+ T helps cells limit exhaustion of memory CD8+ cytotoxic T lymphocyte (CTL) during influenza A virus infection, and Tregs were most important for calming inflammation during the resolution phase of viral infection." (PMID 32419639, 2020). "Of note, CWDP was not capable of enhancing IL-10 levels or lung CD3+CD4+IL-10+ T cells, which was in line with their lower ability to reduce lung damage parameters during bacterial and viral infections when compared to viable D. pigrum 040417." (PMID 32414154, 2020). "Moreover, both CD4 and CD8 are similarly influenced by genetics and external triggers such as vitamin D and viral infections, known to play a role in MS23." (PMID 31427643, 2019). "Having established that miR-155 in CD4+ T cells is important for APC-mediated proliferation and cytokine production in vitro and in vivo, we asked, whether this is relevant during viral infection." (PMID 31275315, 2019). "However, it is unclear to what degree the downregulation of CD4 and CCR5 contributes to the regulation of viral infection in the presence of arsenic trioxide and ART." (PMID 31380187, 2019). "Besides, since we have recently described that CD4+ T cells expressing CD32dim are enriched in HIV transcripts in vivo, and that viral infection upregulates this marker, we analyzed the expression of CD32dim in viral-reactivated cells using different LRAs." (PMID 31425551, 2019). "However, we have recently demonstrated by transcriptome analysis that CD4+ T cell help optimizes the quality of the primary CTL response after both DNA vaccination and virus infection, by similar molecular mechanisms." (PMID 31797935, 2019).
viral infection (continued). "Seemingly uncommitted Th0 cells are not typically observed in acute viral infections, but a similar population lacking either Th1 or Tfh characteristics has been described in CD4+ T cells primed during the chronic phase of LCMV Cl13 infection." (PMID 29951052, 2018). "The role of CD4 and CD8 T cells in immune control of viral infections is well established." (PMID 30315476, 2018). "However, both α-CD4-treated and α-CD8-treated mice were unable to clear viral infection in the periphery." (PMID 30487575, 2018). "The adoptive transfer studies revealed that CD4 T cells alone were not sufficient to control viral infection, whereas the addition of ILC1s resulted in a significantly decreased viral burden." (PMID 29623077, 2018). "In addition, specific ablation of either Tcf1 or Ezh2 in mature CD4+ T cells impaired TFH differentiation, and targeting both proteins almost completely abrogated the TFH cell formation and Bcl6 induction elicited by viral infection." (PMID 30575739, 2018). "Indeed, type III IFNs not only promote a robust immune response by type 1 helper CD4+ and CD8+ T cells, but are also responsible for recruitment and activation of CD4+ T cells after viral infection." (PMID 29706891, 2018). "Not only for PRV, but also for porcine rubulavirus infection, CD4+CD8+ cells have been reported and may participate in the defense against virus infection." (PMID 30705681, 2018). "We, therefore, decided to deplete CD4 and CD8 cells in three C57BL/6J mice by using anti-mouse CD4 (Clone GK1.5) and anti-mouse CD8 (clone 2.43 against CD8a) for seven weeks following anal viral infections." (PMID 29208932, 2017). "To understand the mechanisms underlying the increased levels of Th1 and CD8+ T cell responses producing IFN-γ, we assessed the proportions of CD4+ and CD8+ T cells as well as CD11b+ macrophages/microglia in the CNS in the early stage of viral infection, at 8 dpi." (PMID 28445497, 2017). "In addition to T-cell lymphopenia affecting both the CD4+ and CD8+ compartment, virus infection also revealed a redundant role of PARP-1 and PARP-2 in T-cell effector function." (PMID 28181505, 2017). "Although it is still unclear whether the CD4 CTLs generated in chronic and acute influenza infection have the same characteristics, these results indicate that CD4 CTL can be generated during both chronic and acute virus infections." (PMID 28280496, 2017). "Moreover, CD4+CD25+Foxp3+Treg cells contribute to the adaptive and innate immune responses during acute viral infection." (PMID 28265274, 2017). "Their data highlight the rareness of antigen-activated cytokine producers detectable in peripheral blood, never exceeding 0.5% cytokine producer of total CD4+ T cells throughout the course of an acute, experimental virus infection." (PMID 28567041, 2017). "In this review, we focus on cytotoxic CD4 T cells in the context of human viral infections and in some infections that affect mice and non-human primates." (PMID 28167943, 2017). "These CD4 CTL have been identified in response to a plethora of viral infections affecting mice, non-human primates, and humans, and many aspects of their role in immunity remain unanswered." (PMID 28167943, 2017). "Interestingly, CRTAM+ CD4 cells are found preferentially in the lung and intestinal lamina propria, the same tissues in which CD4 CTL are efficiently generated during viral infections in murine models (discussed further below)." (PMID 28167943, 2017). "Thus, maintaining antiviral CD4 and CD8 T cell effector functions is vital to the control of chronic viral infection." (PMID 28715493, 2017). "Overall, CD4+ CTL appear to be involved in the recognition and the elimination of virus-infected cells in the manifold response activated by the immune system during viral infections." (PMID 28289418, 2017).
viral infection (continued). "Circulating T cells expressing CD38 during infection have been associated with a recently activated effector phenotype; and antigen-specific CD4+ T cells have been shown to express high levels of CD38 and produce IFN-γ in the acute phase of several viral infections including EBV, HIV and Influenza." (PMID 27662621, 2016). "On day 14 p.i., total virus infection-induced (CD44hiCD11ahi) and epitope-specific (GP61-80) effector CD4 T cells showed marked reductions in both the proportion of Blimp-1-eYFP+ cells and per-cell expression of Blimp-1-eYFP following administration of α-IFNAR to LCMV clone 13-infected mice." (PMID 27732671, 2016). "This provides further evidence suggesting that prolonged clinical pathology observed at the site of viral infection in O mice is probably not mediated by CHIKV-specific Th1 CD4+ or CD8+ T cells, as their numbers and function are decreased in aging." (PMID 27736984, 2016). "The current study shows that exposure to AvCystatin leads to enhanced recruitment of IL-10-producing CD4+ T cells in viral infection; however, FoxP3 expression did not coincide with IL-10 production in the regional lymph nodes." (PMID 27560829, 2016). "To test the function of the adaptive immune system in a setting where all virally infected cells are Ifnar1-sufficient, we utilized a previously published Rag1-/- splenocyte transfer in which CD4 T cells and CD8 T cells contribute to clearance of viral infection." (PMID 27327515, 2016). "As we have previously observed, immediately following viral infection the absolute number of LCMV specific CD8+ and CD4+ memory T cells within the spleen rapidly declines; after 24 hours, virus specific T cells were reduced approximately 4- to 10-fold in Cre- mice (white bars)." (PMID 27580079, 2016). "However, the impaired CTL functionality could be reversed by transfer of naïve polyclonal CD4 T cells from wild-type mice highlighting the functional plasticity of these cells which might be exploited for future vaccination strategies or therapeutic options in chronic viral infections." (PMID 28066432, 2016). "A primary cell model of HIV-1 latency, which incorporates the generation of primary central memory CD4 T cells (TCM), full-length virus infection (HIVNL4-3) and ART to suppress virus replication, was used to investigate the establishment of HIV latency using RNA-Seq." (PMID 27898737, 2016). "This indicates that the defect in IL-21 signaling that results in reduced viral infection is intrinsic to B cells and not due to a role for IL-21 signaling in CD4 T cells." (PMID 25875847, 2015). "On the one hand, vigorous CD4+ and CD8+T-cell responses emerge in many acute virus infections." (PMID 25836633, 2015). "A similar apparent increase of non-proliferating CD4+ memory T cells specific for TT was observed in healthy subjects undergoing primary vaccination with the yellow fever vaccine, but no further phenotypic characterization of those cells was performed." (PMID 26332995, 2015). "In this regard, SAMHD1 has been previously reported to suppress virus infection in resting but not in cycling CD4+ T cells." (PMID 25996507, 2015). "In convalescent phase only infants with other viral infections (48.03%) managed to develop increased percentages of CXCR3+CD4 TEM, while children with RSV infection showed only tendency to develop increased percentages of CXCR3+CD4 TEM cells." (PMID 25013801, 2014). "Recent data indicates that CD4 CTL generated during viral infection express Blimp-1 and T-bet transcription factors, but not Eomes." (PMID 24586481, 2014). "It has been demonstrated in models of viral infection that lack of CD4+ help can upregulate PD-1 expression on CD8+ T cells leading to diminished anti-viral responses and a decrease in central memory CD8+ cells." (PMID 25119341, 2014). "Viral infection without CsA resulted in a 15.3- and 12.8-fold increase in CD4+ and CD8+ T cell numbers, respectively, compared to mock-infected littermates." (PMID 25121947, 2014).
viral infection (continued). "The observation of increased frequencies of Ki-67+ CD4+ TCM and TSCM in VNP raises the possibility that these cells may be potential targets for virus infection as a result of their proliferation state." (PMID 25167059, 2014). "To ensure that p24 expression corresponded to productive virus infection and not virus bound to the cell surface we used CD4 down-regulation as a confirmatory sign of virus replication." (PMID 24282561, 2013). "It is possible that although CD4 repopulation following cART may provide added protection against HIV replication, this repopulation also may present additional targets for viral infection." (PMID 24098586, 2013). "Taken together they argue the role of CSFT in T cell function is complex and may be differentially regulated between CD4+ and CD8+ T cells during viral infection and autoimmunity." (PMID 24236211, 2013). "As this viral infection is not consistently present in aging, it is unsurprising that the relationship of inverted CD4+:CD8+ ratios with mortality has been absent in some cohorts." (PMID 23915335, 2013). "It has been hypothesized that CD4 + CD28null T-cells might play a role in containing viral infections tropic for HLA class II cells, such as EBV in B cells, HIV-1 in activated CD4+ T-cells, monocytes and DCs, and CMV in endothelial cells." (PMID 23675374, 2013). "None of the five naïve donors gave either CD4 or CD8 T cell responses against Yellow Fever derived peptides (data not shown)." (PMID 22347475, 2012). "Compensation of CD4 T-cell function by other immune cells was not likely, because wild-type mice depleted of CD4+ T cells were also resistant to viral infection." (PMID 23133489, 2012). "Our findings indicate that low doses of the CB2R agonist JWH-133 are sufficient to inhibit viral infection without significant disruption of CD4+ T cell co-receptor expression, CD4 expression, CD25 upregulation, or proliferation." (PMID 22448282, 2012). "The results indicated that infiltration into the CNS of granulocytes, NK cells, macrophages and CD8+ T cells but not CD4+ T cells was elevated, particularly at the early stage of viral infection." (PMID 22985464, 2012). "Transient lymphocytopenia and CD4+ T lymphocytopenia without clinical immunodeficiency have been seen in a variety of conditions such as bacterial, parasitic, fungal and viral infections." (PMID 24893304, 2012). "In other disease models, such as viral infection where CD8+ T cells play an important effector role, CD4+ T cells contribute essentially to the mobilization of CD8+ T cells to the site of infection through secretion of IFN-gamma and the induction of local chemokine secretion in the infected tissue." (PMID 22916101, 2012). "Further, CB2R agonism did not alter the ability of the CD4+ T cell to support viral infection, as JWH-133 treated cells are readily infected by the CCR5-tropic JRFL virus." (PMID 22448282, 2012). "In this study, the mice treated with 6-OHDA displayed an increased in the spleen B cells, BM early B cells and CD4+CD8+ thymocytes (data not shown) within H9N2 virus infection." (PMID 23251416, 2012). "As CD4+ immune T cell responses include both helper and cytotoxic functions, viral mechanisms for interfering with MHC class II antigen presentation to CD4+ T cells have the potential to greatly influence the outcome of viral infections." (PMID 22216005, 2011). "Likewise, in human viral infections (HCV and HIV) upon antigen exposure, DP T cells displayed a much higher frequency of cell-single cytokine production than CD8+ and CD4+ T cells." (PMID 21886854, 2011). "Studies in mouse models of chronic viral infections have shown that efficient CD8 responses do not persist in the long term without CD4 help." (PMID 20195518, 2010). "Indeed, the CD4/CD8 ratio has been shown to increase in autoimmune diseases and to decrease during viral infections, but remains unaffected in HAT." (PMID 19584913, 2009).
viral infection (continued). "Despite the gp120 binding capacity of CD4 and the functional expression of co-receptors, the trophoblast cells do not show any viral infection when exposed to the X4 and R5 HIV-1 pseudotypes." (PMID 19445667, 2009). "Thus, memory CD4+ T cells, like memory CD8+ T cells, elaborate IFNγ within hours of secondary viral infection." (PMID 18404208, 2008). "One possibility is that during viral infection B cells specific for VP2 phagocytose the complete TMEV virion and present another non‐VP2‐specific class II epitope to CD4+ helper cells, thereby providing the necessary CD4 helper response necessary for maturation of the antibody response." (PMID 17388949, 2007). "In infected B6, Kb−/−xDb−/−, and Kb−/−xDb−/−xCD1d−/− mice, however, the percentages and absolute numbers of both CD4 and CD8 T cells were similar, indicating that viral infection stimulated a massive expansion of CD8 T cells in mice lacking the Class Ia and CD1d molecules." (PMID 16733540, 2006). "We also observed a population of naïve CD4 T cells (denoted ‘Xcl1+ naïve’) expressing Lef1 and Sell genes along with Xcl1, which is a ligand of XCR1 (or G protein-coupled receptor 5, GPR5), with increased expression on NK and CD8+ T cells during virus infection." (PMID 40096073, 2025). "Altogether, our data indicate that mpox co‐infection induces long‐lasting changes in CD4+ T‐cell homeostasis and impacts HIV‐1 reservoir dynamics, providing insights into how secondary viral infections may modulate reservoir persistence and immune competence in PWH." (PMID 41204857, 2025). "In line with previous studies on viral infections, neutralization of IL-12 did not significantly alter CD4+ T cell differentiation, prompting us to explore the influence of another cytokine known for reinforcing TH1 identity through positive feedback loops, IFN-γ." (PMID 40169810, 2025). "Similarly, lack of CD4+ T cell help contributes to CD8+ T cell dysfunction in human chronic viral infections." (PMID 40777021, 2025). "In the present case, cephalexin was administered in the presence of viral symptoms, which may have resulted in excessive activation of CD4+ and CD8+ T-cells due to the viral infection, coupled with an immune response to the drug, ultimately leading to AGEP onset." (PMID 40125151, 2025). "Similar to CD8+ TRM cells, the transition of activated CD4+ T cells into Th1-TRM cells also depends on their interaction with local inflammatory (IL-2 and IL-1) and survival (IL-15) cytokines in microenvironment of livers and lungs during bacterial and viral infections." (PMID 40391228, 2025). "Whether Tph-like CD4+ T cells that produce CXCL13 are a common feature of virus infections is not known." (PMID 40956619, 2025). "Together, our results indicate that a main function of CD4+ T cells during acute hepacivirus infection is to provide help in T cell priming and that, unlike in some other viral infections, the primary anti-hepaciviral effector T cell response is help dependent." (PMID 39392861, 2024). "The abundance of circulating CD4+ T cells increased at 14 and 21 DPI, either indicating that the potency of the mAb treatment was waning despite repeated injections and/or reflecting changes in T cell abundance that had occurred in response to the viral infection." (PMID 39495799, 2024). "Specifically, among these patients, a lower CD4+/CD8+ ratio was correlated with larger left ventricular and ventricular system volumes, which could potentially be attributed to persistent inflammation and immunosenescence induced by viral infection." (PMID 38921466, 2024). "Moreover, a low or mere expression of CD4 is not sufficient for productive viral infection, as CD4+ HeLa, Jurkat, and THP1 cells do not support productive viral replication." (PMID 38717112, 2024).